RN7SKP270 (RN7SK pseudogene 270)
Gene: Miscellaneous RNA gene on chromosome 1 (96,695,856 to 96,696,167, reverse strand). Ensembl gene ENSG00000223229.
Homologues: Orthologues: chimpanzee 7SK (98% identical). Paralogues in human: RN7SKP90 (66% identical), RN7SKP133 (63% identical), RN7SKP33 (63% identical), RN7SKP86 (62% identical), 7SK (62% identical), RN7SKP79 (62% identical), RN7SKP124 (62% identical), RN7SKP146 (62% identical), RN7SKP180 (62% identical), RN7SKP184 (62% identical), RN7SKP203 (62% identical), RN7SKP222 (62% identical), and 284 more.